NANOG (Nanog homeobox)
Diseases named in the same sentence as NANOG in open-access papers (continued):
Sharing a sentence is not in itself a finding about the gene and the disease.
colon carcinoma (41 papers, 2013 to 2025). "In colon cancer, increased levels of NANOG expression are associated with advanced cancer stages and a poor prognosis." (PMID 34452555, 2021). "Accordingly, while NANOG is silenced in normal cells, its abnormal expression has been reported in various human cancers, and was associated with poor prognosis and lower survival rate in colon cancer patients." (PMID 35267511, 2022). "CD44v6 is a biomarker associated with colon cancer stemness and tumor progression, and hyaluronan-engaged CD44v3 induces the expression of stem cell markers, NANOG, SOX2, and OCT4, promoting tumor progression and chemoresistance of head and neck squamous cell carcinomas." (PMID 33804427, 2021). "We found that all 7 N-glycosylation sites are involved in the regulation of the stem cell properties of colon cancer stem cells by NANOG protein." (PMID 41264633, 2025). "To evaluate the clinical significance of NANOG upregulation in colon cancer, we analyzed the expression of N-glycosylases in colon cancer tissues from the Gene Expression Profiling Interactive Analysis (GEPA) database." (PMID 41264633, 2025). "MTT assay was used to detect the effects of seven different N-glycosidic sugar mutants at the carboxyl terminus of NANOG protein on the proliferation of colon cancer stem cells." (PMID 41264633, 2025). "The WT plasmid and 7 mutant plasmids of NANOG protein were transfected into CD133 + stem cells in magnetic bead-sorted HCT116 colon cancer cells and cultured for 24 hours." (PMID 41264633, 2025). "ChIP assay was performed to confirm the interaction of c-Fos with promoter of NANOG in colon cancer cells." (PMID 38233377, 2024). "Collectively, these results indicate the essential role of NANOG in mediating the effects of c-Fos/p-c-Fos on promoting stemness and 5-FU resistance in colon cancer." (PMID 38233377, 2024). "Subsequently, ERK1/2 phosphorylates and activates c-Fos, which increases cell stemness and confers 5-FU resistance through the upregulation of NANOG in colon cancer." (PMID 38233377, 2024). "In sum, these results confirmed that c-Fos was involved in inducing 5-FU resistance by regulating NANOG and augmenting cancer cell stemness in colon cancer cells." (PMID 38233377, 2024). "Mechanistically, our results unraveled that c-Fos enhanced cell stemness in colon cancer via direct up-regulation of the transcription factor NANOG." (PMID 38233377, 2024). "Taken together, these findings revealed that TMPO-mediated phosphorylation of c-Fos conferred 5-FU resistance by regulating NANOG expression and promoting cell stemness in colon cancer cells." (PMID 38233377, 2024). "Mechanistically, overexpression of c-Fos was found to induce the resistance to 5-FU in colon cancer cells by augmenting cancer stemness through the direct regulation of the pluripotent transcription factor NANOG." (PMID 38233377, 2024). "We found that c-Fos promotes the cell stemness by directly binding to the promoter of NANOG, which leads to increased NANOG expression and consequently confers 5-FU resistance in colon cancer." (PMID 38233377, 2024). "The present study provides the first evidence that TRRAP plays an important role in the tumorigenic ability of colon cancer cells by regulating NANOG protein stability." (PMID 37047234, 2023). "We also demonstrated that NANOG is essential for maintaining the CSC-like properties of colon cancer spheroids." (PMID 37047234, 2023). "Together, these results suggest that TRRAP plays a pivotal role in the regulation of the tumorigenic potential of colon cancer cells by modulating NANOG protein stability." (PMID 37047234, 2023). "The mRNA expression of the CSC markers, LGR5 and NANOG, were significantly induced in the spheres of the colon cancer cell lines SW480, SW620, CT-26 and HT-29, compared to their parental cells." (PMID 35267511, 2022).
colon carcinoma (continued). "In our study, we found that the reduced ability of colon cancer with inhibited PCs activity to mediate tumor growth was associated with reduced expression of the CSC markers LGR5 and NANOG." (PMID 35267511, 2022). "Further analysis revealed that reduced tumor growth mediated by specific silencing of the convertase Furin in KRAS or BRAF mutated-induced colon tumors was associated with reduced expression of LGR5 and NANOG compared to wild-type KRAS and BRAF tumors." (PMID 35267511, 2022). "In colon cancer cells, NANOG increases FAK expression, and FAK’s phosphorylation is a component of the signaling loop that increases NANOG activity." (PMID 36407100, 2022). "NANOG expression is likely functionally crucial in colon cancer, as overexpression of the NANOG gene increases the proliferation of cancer cells." (PMID 34452555, 2021). "siRNA-depletion of Syndecan-1, and upregulation of heparanase increased the colon cancer stem cell phenotype based on sphere formation assays and phenotypic marker analysis (Side-population, NANOG, KLF4, NOTCH, Wnt, and TCF4 expression)." (PMID 32477959, 2020). "To further explore direct transcriptional targets of FRA1 in the regulation of colon cancer stemness, we analyzed NANOG protein expression in FOSL1-overexpressing DLD1 and HT-29 cells by western blot." (PMID 30804456, 2019). "The stemness of colon cancer stem cells were found to be associated with higher expression of CD133, ALDH, NANOG, OCT4 and SOX-2, and these markers are found connected to the drug resistance of cancer cells." (PMID 31349708, 2019). "Previous studies indicated that NANOG is expressed in colon cancer cells, and suggested that their expression contributes to proliferation of colon cancer cells." (PMID 24586330, 2014). "A pro-metastatic role of NANOG in colon cancer cells was also demonstrated, using a NANOG-overexpressing orthotopic tumor implantation mouse model." (PMID 24023739, 2013). "It was then hypothesized that p-c-Fos-mediated transcription and expression of NANOG promote stemness and resistance to 5-FU in colon cancer." (PMID 38233377, 2024). "Our findings clarified a new molecular mechanism of NANOG regulation in colon cancer." (PMID 38233377, 2024). "The replacement of miR-149, normally suppressed by SNAIL2 in colon carcinoma, was associated with an inhibition of EMT and 5-FU chemo-resistance upon the targeting of MYC and nanog homeobox (NANOG) and with a reduction in glucose metabolism after pyruvate dehydrogenase kinase 2 (PDK2) inhibition." (PMID 34503164, 2021). "Together with the unchanged levels of the colon cancer stem markers NANOG, SLUG and SNAIL, these effects suggest that the increased trend in cell proliferation usually associated with Ki67 and PCNA is not characterized by phenotypic traits suggesting cancer progression, at least in this cell model." (PMID 34987311, 2021). "In colon cancer cells, NANOG was shown to bind the FAK promoter and increase FAK expression." (PMID 32514188, 2020). "Knockdown of STRA6 or RBP4 in SW480 colon carcinoma cells decreased the levels of NANOG and SOX2." (PMID 28689994, 2017). "Experimental results showed that in HCT116 colon cancer stem cells and LoVo colon cancer stem cells, compared with the WT group, the seven MUT plasmid transfection groups of NANOG protein could significantly inhibit the proliferation of colon cancer stem cells." (PMID 41264633, 2025). "In colon cancer, FAK phosphorylation enhanced the activity of the transcription factor NANOG, which activated PTK2 to initiate the NK-κB pathway to support the progression of carcinoma cells." (PMID 39895788, 2025). "After magnetic bead sorting of CD133 + stem cells in HCT116 colon cancer cells and CD133 + stem cells in LoVo colon cancer cells, they were transfected with WT plasmids and 7 mutant plasmids of NANOG protein, respectively, and cultured for 72 hours." (PMID 41264633, 2025).
colon carcinoma (continued). "After magnetic bead sorting of CD133 + stem cells in HCT116 colon cancer cells and CD133 + stem cells in LoVo colon cancer cells, the WT plasmid and 7 mutant plasmids of NANOG protein were transfected respectively and cultured for 72 hours." (PMID 41264633, 2025). "To clarify the role of TRRAP in colorectal CSCs, we measured the expression levels of TRRAP and NANOG in adherent and three-dimensional spheroid cultures of HCT-15 colon cancer cells." (PMID 37047234, 2023). "In colon cancer stem cells, as in ESCs, LINC-ROR acts as a ceRNA to prevent miR-145-mediated suppression of NANOG, OCT4, and SOX2 TFs to regulate cell proliferation and chemosensitivity." (PMID 34439740, 2021). "In fact, in colon cancer cells (Caco-2, LS174T, LoVo, HT-29, HCT116, SW480, and SW620) and human colorectal cancer tissues, NANOG directly represses the transcription of mir-200b/c genes, modulating EMT to mesenchymal–epithelial transition plasticity." (PMID 34439740, 2021). "Moreover, it has been demonstrated that NANOG, a core homeobox transcription factor (TF) playing key roles in the maintenance and preservation of self-renewal in embryonic stem cells (ESCs), is also expressed in CSCs from different tumor types, including liver and colon cancers." (PMID 30804456, 2019). "Consistently higher expression of CD133, SOX2, NANOG, OCT4, CD44 and Lgr5 in ALDH+ cells, which was the representative markers of CSC, validated the truth of stemness of ALDH+ colon cancer cells." (PMID 30962766, 2019). "Previous studies have shown that the colon cancer stem cells isolated from HCT116 cells express high levels of PROM1 (CD133), CD44, EPCAM, SOX2, c-MYC, and NANOG." (PMID 29507661, 2018). "In colon cancer, DOT1L increases cancer stemness and tumorigenic potential by inducing the core stem cell genes NANOG, SOX2 and Pou5F1." (PMID 27581651, 2016). "The expression profile of stem cell and CSC markers genes of BORIS-depleted spheres showed that NANOG, OCT4 and SOX2 genes were down-regulated in both breast and colon tumor cells." (PMID 26185996, 2015). "The results showed that the apoptosis levels of HCT116 colon cancer stem cells and LoVo colon cancer stem cells after transfection of 7 MUT plasmids of NANOG protein decreased, indicating that N-glycosylation enhances NANOG-mediated apoptosis of tumor stem cells." (PMID 41264633, 2025). "Following the enhancement of NANOG expression, there appeared increased expressions of BMI and SNAIL1/2, followed by the suppression of E-cadherin expression in various cancer cells (glioblastoma, non-small lung cancer, HNSC, colon cancer, and A549)." (PMID 36497144, 2022). "In colon cancer, LGR5 and NANOG are assumed to be stem cell markers." (PMID 36497144, 2022). "To further understand the details of the stem gene expression, we measured the gene expressions of signature stem and self-renewal genes (including OCT4, NANOG, C-Myc, CD133, Lgr5, TGF-β1, and SHP2) of colon cancer in the treated cells with the optimised conditions." (PMID 36612229, 2022). "While FAK is known to phosphorylate NANOG in colon cancer cells, FAK activity was not required for the formation of the Cx26/FAK/NANOG complex in TNBC CSCs15." (PMID 32514188, 2020). "Moreover, western blot and qRT-PCR results showed BCAR4high cells showed higher expression of NANOG, OCT4, SOX2, CD44, CD133 and Lgr5 which are important markers of CSC in colon cancer." (PMID 30962766, 2019). "For example, NANOG promotes but is not required for colon cancer xenograft growth." (PMID 30846719, 2019). "FAK and NANOG were shown to colocalize to the nucleus, but the Y35F and Y174F NANOG mutants showed decreased nuclear localization, suggesting that FAK phosphorylation and interaction may regulate NANOG nuclear translocation and transcriptional activity in colon cancer cells." (PMID 32514188, 2020).
colon carcinoma (continued). "Finally, whereas the number of putative U251 CD133+ colon cancer stem cells (4%) was unaffected, the number of clonal spheroids was drastically reduced upon NANEP5 expression either upon diluted single cell or in bulk conditions, much as reported for NANOG kd18,27." (PMID 30846719, 2019). "Our results uncovered that NANOG, rather than KLF4, OCT4, and SOX2, was significantly up-regulated in FOS-overexpressed colon cancer cells." (PMID 38233377, 2024). "We next analyzed in colon cancer cells the expression of LGR5, NANOG, OCT-4, and SOX2 in the presence and absence of α1-PDX." (PMID 35267511, 2022).
pancreatic cancer (40 papers, 2014 to 2025). "A meta-analysis of 2 data sets from 90 pancreatic cancer patients linked elevated NANOG expression with poor overall survival." (PMID 31624231, 2019). "For example, lncRNA ROR, acted as a ceRNA of miR-145, could regulate NANOG expression level and was associated with poor survival of pancreatic cancer." (PMID 27528026, 2016). "We found that the expression of genes characteristic of early stem cells, NANOG (p = 0.03), and the expression of genes encoding insulin and cytokeratin 19 (INS p = 0.02, CK19 p = 0.005) were increased in pancreatic cancer patients." (PMID 40699634, 2025). "Expression of stemness genes, particularly NANOG, was significantly reduced after pancreatic cancer cell exposure to TH301 (40 μM; 24 h)." (PMID 39796036, 2024). "CSCs obtained from primary patient-derived pancreatic cancer cells showed a positive correlation between higher telomerase activity and longer telomeres and stemness factors (NANOG, OCT3/4, SOX2, KLF4)." (PMID 37239940, 2023). "The TGF-β pathway is increasingly associated with stemness in pancreatic cancer, promoting the number of CD133+ pancreatic CSCs and upregulating stemness-related genes such as CD24, NANOG, and SOX2." (PMID 33562727, 2021). "For example, in the context of TAMs supporting stemness in colorectal cancer, the most prominent pathway is SHH, in pancreatic cancer is the TGFβ/ SMAD2/3/NANOG, and in hepatocarcinoma is the NOTCH pathway." (PMID 34583655, 2021). "The extract also inhibited CD44+/CD24+/EpCAMhigh pancreatic cancer stem cell (CSC) populations, CSC-associated markers SOX2, OCT4, NANOG and CD44 in-vitro and in-vivo, and increased sensitivity to gemcitabine." (PMID 32726914, 2020). "The results suggest that NANOG acts as an oncoprotein in pancreatic cancer, and reducing its expression weakens the cancer phenotype." (PMID 31624231, 2019). "Here we provide evidence that, SPOP-NANOG interaction allows SPOP to control NANOG activity and reduce its oncogenic potential in pancreatic cancer." (PMID 31624231, 2019). "We showed that the low SPOP expression and the SPOP mutant lead to decreased repression of NANOG, which can then promote pancreatic cancer cell proliferation, migration and invasion." (PMID 31624231, 2019). "Our results suggest that SPOP suppresses progression of pancreatic cancer by promoting the ubiquitination and subsequent degradation of NANOG." (PMID 31624231, 2019). "BBR has been shown to suppress genes associated with stemness such as SOX2, POU5F1, NANOG and NOTCH in the side population of certain pancreatic cancer cell line PANC-1." (PMID 28611316, 2017). "It has been shown that knockdown of OCT4 and NANOG in pancreatic cancer cells reduced their proliferation, migration, invasion, chemoresistance, and tumorigenesis." (PMID 25477962, 2014). "It has been illustrated that the upregulation of LINC-ROR is associated with cell proliferation, EMT, migration, invasion, metastasis, poor prognosis, inhibition of NANOG expression, and alteration of cancer stem-like cells properties via the regulation of miRNAs in pancreatic cancer." (PMID 33745265, 2021). "Then, we wondered whether known factors regulating mitochondrial biogenesis and NANOG expression could be overexpressed in pancreatic cancer cells as adaptation to AKT signaling." (PMID 32764385, 2020). "To examine how the patient-derived Q360* mutation may disrupt the tumor-suppressive role of SPOP in pancreatic cancer, we transiently upregulated expression of SPOP-WT or SPOP-Q360* in cells overexpressing NANOG." (PMID 31624231, 2019). "In the current study, Sox2, Oct-4, ABCG2, and NANOG were simultaneously upregulated in miR-629-overexpressed pancreatic cancer cells, and the expression of p21 and p27 was inversely correlated with the expression of miR-629 in pancreatic cancer cells." (PMID 29072689, 2017).